IL10 (interleukin 10)
Diseases named in the same sentence as IL10 in open-access papers (continued):
Sharing a sentence is not in itself a finding about the gene and the disease.
Hodgkins lymphoma (21 papers, 2009 to 2025). A heterogeneous group of malignant lymphoid neoplasms of B-cell origin characterized histologically by the presence of Hodgkin and Reed-Sternberg (HRS) cells in the vast majority of cases. "One study on Hodgkin’s disease also associated high IL-10 levels with poor survival." (PMID 39199610, 2024). "The shed form of CD163 is upregulated in a large range of inflammatory diseases and Hodgkin lymphoma, is induced by anti-inflammatory factors such as IL-6 and IL-10, and is known to be upregulated in PCNSL." (PMID 29299134, 2017). "Elevated levels of IL-1β, TNF-α, IL-6, IL-8, and IL-10 are detected in the serum of patients with EBV-associated diseases, while a less favorable outcome correlates with increases of IL-6 and IL-10 in Hodgkin's lymphoma." (PMID 23346088, 2012). "Additionally, inhibition of HDAC11 in Hodgkin lymphoma increases the expression of OX-40 ligand and inhibits the generation of IL-10 producing T regulatory cells in vitro." (PMID 25054063, 2014). "We analyzed the distribution of circulating B-lymphocytes and the level of the activating cytokines IL6, IL10 and BAFF in 38 patients with HIV-related Hodgkin’s lymphoma during a 2-year follow-up." (PMID 35008292, 2021). "In a cohort of Hodgkins lymphoma patients, an argument was made by Marshall and colleagues for a contributory role of CD4+ IL-10+ Tr1 cells toward ineffective clearance of Hodgkins lymphoma." (PMID 23874336, 2013). "Previous study also showed that the chemotherapy-sensitive Hodgkin lymphoma patients had frequent gains of 16q13, a chromosomal region known to house genes that regulate T-cells trafficking or NF-ĸB activation (CX3CL1, CCL22, CCL17, DOK4, and IL10)." (PMID 37153002, 2023). "In addition, a high frequency of Tr1 cells was reported in Hodgkin Lymphoma and HCC patients with a high suppressive activity mediated through IL10." (PMID 25525301, 2014).
meningitis (21 papers, 2009 to 2025). A disorder characterized by acute inflammation of the meninges of the brain and/or spinal cord. "have also found inflammatory markers elevated in the CSF during VZV-related meningitis, including interferon gamma, interleukins IL-6, IL-8, IL-10, IL-17F, IL-1RA, chemokines CXCL-9, CXCL-10, CCL-2 and G-CSF." (PMID 40416981, 2025). "As expected, in the PFC, we observed increased levels of pro-inflammatory cytokines such as IL1-α, IL1-β, IL-6, IL-17, TNF-α, and INF-γ (P < 0.05) and decreased levels of IL-7, IL-10, and IL-13 (P < 0.05) in the 24-h meningitis group." (PMID 31901235, 2020). "Two-way ANOVA indicated interactions significant between the variables (MyD88 and meningitis) on these inflammatory mediator productions (except expression of IL-10 in cortex)." (PMID 28615695, 2017). "To determine whether the immune system is affected by PLG and induces meningitis symptoms, we investigated the expression levels of EV-A71-associated cytokines such as IL-1β, IL-6, MCP-1, IL-10, and IFN-γ in serum after EV-A71 infection." (PMID 40377310, 2025). "Moreover, in an E. coli-induced meningitis model in mice, IL-10 promoted CR3-mediated bacterial clearance by phagocytosis by reducing prostaglandin E2 (PGE2) production." (PMID 32153580, 2020). "In murine S. pneumoniae meningitis, the absence of IL-10 was associated with higher proinflammatory cytokine and chemokine concentrations and more pronounced infiltrates." (PMID 25563481, 2015). "Of the 13 measured, 11 (GM-CSF, IFNγ, IL-1α, IL-1Β, IL-2, IL-4, IL-6, IL-10, IL-12, IL-18, and TNF-α) exhibited higher concentrations in the saliva of pigs with meningitis and S. suis infection." (PMID 40284818, 2025). "This is inconsistent with our observation that IL-10 can be elevated in conditions other than PCNSL, such as meningitis and T-cell lymphoma with leptomeningeal involvement." (PMID 27924864, 2016). "Here, we show for the first time that during meningitis cytokine and chemokine levels also positively correlate with the bacterial burden in the brain of wild-type mice (id est IL-6, TNF-α, IL-1β, IL-10, KC, and MIP-2)." (PMID 25958220, 2015). "Previous works have investigated the CSF levels of inflammatory cytokines and chemokines in patients with meningitis, such as IL-6, IL-1β, TNF-α, IL-10, chemokines of the CXC family (IL-8) and growth factors using immunoenzymatic methods." (PMID 26040285, 2015). "When a panel of cytokines (including GM-CSF, IFNγ, IL-1α, IL-1β, IL-1ra, IL-2, IL-4, IL-6, IL-8, IL-10, IL-12, IL-18, and TNF-α) was measured in saliva from healthy pigs and in pigs with meningitis and S. suis infection, upregulation of several cytokines was observed in the diseased animals." (PMID 40284818, 2025). "A previous study showed that IL-10 suppressed PGE2 production, which resulted in enhanced clearance of E. coli by promoting the bacterial phagocytosis by neutrophils and macrophages through a CR3-dependent manner in a meningitis model." (PMID 32153580, 2020). "First, in Rubenstein’s study, IL-10 was not sufficiently specific to differentiate between patients with PCNSL versus CNS infections/inflammation (CSF IL-10 was positive in 4 out of 12 cases with meningitis)." (PMID 27924864, 2016). "However, such a correlation is not observed for IL-6, IL-10, and KC in C/EBPδ−/− mice, which suggests that C/EBPδ directly drives transcriptional activity of these inflammatory mediators during meningitis." (PMID 25958220, 2015). "In CSF, IL‐6, IL‐10, and IFN‐γ showed rapidly increase in EVM group while cytokines sharply declined in control group without meningeal infection." (PMID 31912935, 2020). "Microglia of P4 neonates born to NV and LMWT-infected mothers presented high levels of IL-6, IL-10 and TNF-α and lacked production of IL-12p40; a Th2 pattern similar to the cytokine profile reported in meningitis and encephalitic cases of listeriosis." (PMID 28903312, 2017).
meningitis (continued). "To determine the cytokine expression of meningitis, we compared the CSF levels of proinflammatory cytokines IL-6, IL-17, and IFN-γ and anti-inflammatory cytokine IL-10 in patients with non-HIV and HIV-positive CM, TBM, and patients with meningitis-free syphilis." (PMID 35720334, 2022). "The persistence of the infiltrate in Bcl-2 transgenic mice following meningitis in vivo suggested that neutrophils were not taken up by macrophages, and this might result in reduced secretion of TGF-β (IL-10 is not detectable in this model)." (PMID 19478887, 2009). "Interestingly, anti-inflammatory cytokines detected in the CSF of meningitis patients such as IL10, TGFβ or the IL1 receptor antagonists IL1Rs and IL1R2 could not be detected in this study, suggesting that the CP epithelium might not be the source of these factors during meningitis." (PMID 34863201, 2021).
ZIKV infection (21 papers, 2016 to 2026). "Previous cohorts have also reported an increase in serum IL‐10 levels during the early phase of ZIKV infection." (PMID 41556482, 2026). "In contrast, no change in the mRNA levels of anti-inflammatory cytokines transforming growth factor β and IL-10 were seen in skeletal muscle tissue following ZIKV infection compared to mock-treated animals." (PMID 34468171, 2021). "ZIKV infection increases the levels of a series of cytokines (IL-1α, IL-6, IL-9, IL-10, IL-12p70, and IFN-γ) and chemokines (CCL2, CCL3, CCL4, CCL5, CCL11, and CXCL1) in mouse brain." (PMID 34399779, 2021). "We demonstrated that ZIKV infection via the RO and IVag routes generates IL-10-producing Th1 cells, which also possess regulatory activity but are distinct from the CD25+FoxP3+ subset that develops in the thymus." (PMID 30677097, 2019). "Cytokine profiles in acute ZIKV infections were estimated using a multiplex bead analysis assay which measured interleukin (IL) 1β, IL-2, IL-4, IL-6, IL-8, IL-9, IL-10, IL-13, and IL-17." (PMID 30682026, 2019). "This longitudinal follow‐up provides chronological information on the immune response to mild‐to‐moderate ZIKV infection, with an early antiviral response dominated by IFN‐γ, TNF‐α and regulated by IL‐10, followed by a peak of Th1 and then Th17‐associated cytokines that persists for up to 1 month." (PMID 41556482, 2026). "As a pleiotropic molecule, IFN acts synergistically with TNF-α and IL-10, indicating that the tissue’s response to ZIKV infection involves not only attempts to control viral replication but also the recruitment and activation of diverse immune cells at the infection site." (PMID 41474758, 2025). "The samples from pregnant women with ZIKV infection included in this study showed increases in all anti-inflammatory cytokines (IL-10), and some pro-inflammatory cytokines (IL-6, IFN-γ, IFN-α, and IL-17A), chemokines (CXCL10, CCL2, CXCL9, and CXCL8), and receptors (IL-1RA and IL-2R)." (PMID 33430059, 2021). "In addition, ZIKV infection significantly induced seminal inflammatory cytokines including IL-6, IL-10, G-CSF and GM-CSF (ZIKV vs. Mock)." (PMID 29447264, 2018). "IL-10 levels were also highest in the later (recovery) phase of ZIKV infection, as seen in DF." (PMID 26702627, 2016). "Adult ZIKV infection is associated with immune activation with upregulation of cellular markers, including CD69, Ki67 and increases insoluble markers, including MCP-1, IL-2, IL-15, vascular endothelial growth factor (VEGF) and IL-10 in the first few days post-infection." (PMID 35130924, 2022). "In general, ZIKV infection elicited rapid increase in serum cytokines and chemokines (specifically IFNγ, TNFα, MCP-1, IL-15, IL-10, IL1RA, MIP-1β), with responses peaking around 1–2 days post-infection." (PMID 34120576, 2021). "Collectively, these results demonstrate that, at the peak of the T cell response, ZIKV infection induces expansion of Ab-promoting TFH cells and IL-10-producing CD4+ T cells, but suppresses the population of Treg cells." (PMID 30677097, 2019). "Second, only four (TGFα, IL-1RA, IL-10, and MCP-1) of 23 assayed serum cytokines demonstrated significant changes following ZIKV infection, similar to findings in related studies." (PMID 30469417, 2018). "It has been reported that Zika fever increases circulating IL-6 levels without changing IL-10 levels." (PMID 33430059, 2021). "In our study, levels of several immune markers, such as IFN-α, IL-12, IL-6, IL-17, IL-10, IL-5, IL-2R, ST2/IL-1R4, CCL2, CCL3, CXCL9, M-CSF and E-Selectin, were significantly higher in presymptomatic/asymptomatic ZIKV infection (A-ZIKV group) when compared to the NI control group." (PMID 31748599, 2019). "ZIKV infection induced in nonpregnant women significantly higher levels of the anti-inflammatory cytokine IL-10, and increased pro-inflammatory cytokines IL-6, IL-2, IFN-α, and IFN-γ, and decreased levels of IL-1β in relation with uninfected, nonpregnant women." (PMID 33430059, 2021).
ZIKV infection (continued). "We do not know whether lower levels of IL-1β, IL-6, IL-8, IL-10, IL-12, IL-13, IL-17A, TNF, and IFN-γ in ZIKV offspring at 32 days were caused by subclinical in utero ZIKV infection or maternal cytokine background." (PMID 31725819, 2019). "Furthermore, the same authors demonstrated that an Asian lineage ZIKV infection promoted the differentiation of non-classical M2-type, IL-10-expressing immunosuppressive monocytes by inhibiting the IFN pathway." (PMID 31673117, 2019). "ZIKV infection triggered the upregulation of multiple cytokines in humans during acute phase of infection that we were able to characterize by Luminex assay, including IP-10, IL-5, GM-CSF, TNF-α, IL-15, IL-10, MIP-1α, IFN-γ, IL-6, IL-1RA, IL-2, MIG, IFN-α, IL-2R, and IL-4." (PMID 30333476, 2018). "However, as with the cell lines, we did not detect an increase in IL-10 production in monocyte-derived macrophages during ADE of ZIKV infection, which has been suggested to be one of the hallmarks of intrinsic ADE for DENV and seems to contribute to disease severity in severe DENV infections." (PMID 36560779, 2022). "It is possible that a non-increased IL-10 production during ADE of infection is specific for ZIKV as we and others have not observed increased IL-10 production during ADE of ZIKV infection in fetal macrophages and in primary human cells." (PMID 36560779, 2022).
acute myeloid leukemia (20 papers, 2015 to 2025). Acute myeloid leukemia (AML) is a group of neoplasms arising from precursor cells committed to the myeloid cell-line differentiation. "In the context of acute myeloid leukaemia, patients with higher plasma IL‐10 concentrations have prolonged overall survival and greater event‐free survival and remission rates." (PMID 38495918, 2024). "Of interest, an IL17/IL10 double-producing T-cell subset has recently been shown to be immunosuppressive, and promote tumor immune escape in acute myeloid leukemia patients." (PMID 33530408, 2021). "Moreover, in the presence of this engineered IL-10 variant, chimeric antigen receptor (CAR) T cells expanded and exhibited significantly greater cytotoxicity against acute myeloid leukemia cells compared to those cultured with wild-type IL-10." (PMID 40149345, 2025). "Furthermore, in vitro experiments found that IL‐10 inhibited acute myeloid leukaemia blast proliferation and the production of pro‐leukaemic cytokines." (PMID 38495918, 2024). "In addition, in acute myeloid leukemia (AML) patients’ changes in Tregs were not limited to their levels but also their function reflected by higher production of cytokines: IL-10, IL-35, TGF-ß." (PMID 37569699, 2023). "Moreover, CAT-DCs were able to suppress T-cells using indoleamine 2,3-dioxygenase (IDO), and induced IL10/IL17-secreting T-cells—a subtype reported to exert immunosuppression in acute myeloid leukemia." (PMID 33530408, 2021). "Similarly, IL-10 production by acute myeloid leukemia (AML) blasts induces upregulation of NKG2A with significant impairment in NK function." (PMID 26635792, 2015). "For example, the application of CD33-CAR-NK92 cells in patients with relapsed or refractory acute myeloid leukemia (AML) resulted in fever (reaching up to 40°C) and grade I CRS, accompanied by increased serum levels of IL-10 and IL-17." (PMID 40260240, 2025). "In addition, favorable prognostic indicators for survival in patients with acute myeloid leukemia (AML) include reduced levels of IL-6 and elevated levels of IL-10." (PMID 38337668, 2024).
adenoma (20 papers, 2009 to 2026). A neoplasm arising from the epithelium. "Lower IL-10 levels were associated with a higher risk of the disease, but IL-10 levels in adenoma and serrated adenoma were slightly higher than in normal cells." (PMID 35884974, 2022). "Decreased IL-2 concentration during the trial increased the risk of any adenoma recurrence (4th vs 1st quartile, OR=1.68, 95% CI=1.13–2.49), whereas decreased IL-1β or IL-10 reduced the risk of advanced adenoma recurrence (OR=0.37, 95% CI=0.15–0.94; OR=0.39, 95% CI=0.15–0.98, respectively)." (PMID 20924374, 2010). "Our data report that the levels of Th2 cytokines—interleukins-4 and -10 (IL-4 and IL-10)—gradually increase from CR adenoma to CRC." (PMID 40149674, 2025). "Regarding IL-10 levels in premalignant and malignant CR lesions, double immunohistochemistry revealed more abundant CD4/CD25 and IL-10/FoxP3 dual-positive Tregs within the tumor stroma in both adenomas and carcinomas." (PMID 40149674, 2025). "The density analysis disclosed that IL-10 levels are significantly higher in adenoma tissues than in the normal control and slightly higher than in CRC." (PMID 40149674, 2025). "The expression of IL-4, TNF-α, COX-2, and IL-1β is higher in serrated adenomas than in adenomas, but the expression of IL-10 shows the opposite trend." (PMID 35884974, 2022). "So in the adenoma patients, gender-specific Th1/Th2 pathways were involved in the Th1/Th2 network, while IL-10 (immunologically suppressive) was excluded; in the patient group there was an inverted situation." (PMID 22235223, 2011). "The findings imply that the over-expression of IL-10 may be partially attributed to the increased presence of Tregs in CR adenoma during the transition to CRC." (PMID 40149674, 2025). "Besides the clustering of immune cells positive for IL-10 or IL-17 in lymphoid follicles, the IL-10 and IL-17-expressing epithelial cells were also detected within the adenomas of the AOM-DSS-ST11 K. pneumoniae mice." (PMID 34606408, 2021). "YYFZBJS decreased expression levels of Foxp3, IL-6 and IL-10 in conventional T cells in adenomas." (PMID 32677955, 2020). "However, we also detected a significant positive correlation between Fusobacterium and IL-10 expression in adenoma cases." (PMID 23335968, 2013). "Furthermore, the presence of numerous phosphorylated RelA positive immune- and intestinal epithelial cells were observed in adenomas from Il10−/− mice." (PMID 19551144, 2009). "Going back to the data, we then quantified the ratio of immunosuppressive cytokines (TGF-β, IL-10) to inflammatory cytokines (TNF-α) in benign and progressed adenomas." (PMID 35379804, 2022). "Analysis of TNF-α, CXCL1, IL-1β, IL-10 protein and TGF-β mRNA levels in colonic tissue segments devoid of obvious adenomas revealed the expected increases in these cytokines in the AOM/DSS mice were not affected by M(IL4) treatment." (PMID 34691050, 2021). "Specifically, we assessed mRNA expression of mucosal inflammatory cytokines IL-6, IL-10, IL-12, IL-17 and TNF-α in normal rectal biopsies and correlated their expression levels with abundance of Fusobacterium species in adenoma and non-adenoma subjects." (PMID 23335968, 2013). "Unlike clinical settings, Il-10 appears to induce a protective effect against adenoma development in similar APC-flox animal models through the regulation of the microbiota by T cell populations." (PMID 37373142, 2023). "The observed increases of Il-10 expression in large adenomas with TH1 responses suggest that VAX014 does not overtly disturb the normal immune homeostasis required to maintain colon health." (PMID 37373142, 2023).